CDKN2A (cyclin dependent kinase inhibitor 2A)
Diseases named in the same sentence as CDKN2A in open-access papers (continued):
Sharing a sentence is not in itself a finding about the gene and the disease.
lung carcinoma (250 papers, 2004 to 2026). "In LUAD, some study has shown that the frequency of CDKN2A mutations is higher in lung carcinoma tissues than in tumor-adjacent normal tissues, indicating that CDKN2A mutations can be associated with tumorigenesis." (PMID 41341386, 2025). "In patients with stage I–III lung cancer, CDKN2A deletion has been linked to poorer disease-free survival." (PMID 39323996, 2024). "The lung cancer data retrieved from the TCPA database showed that lower expression levels of p16/CDKN2A protein was associated with poorer OS." (PMID 39323996, 2024). "It was discovered that the CDKN2A gene's mutation rate in lung cancer tissues was greater than that in nearby tissues, and that patients with CDKN2A mutations had higher recurrence rates than patients with wild-type CDKN2A." (PMID 38206516, 2024). "CDKN2A inactivation is common in lung cancer, caused by homozygous deletion, promoter region methylation, or point mutations." (PMID 39323996, 2024). "The expression level of cyclin-dependent kinase inhibitor 2 A (CDKN2A) was linked to cuproptosis in M2 cells in pulmonary fibrosis, although its role in lung cancer remains to be determined." (PMID 39068453, 2024). "Alterations in other cyclin-dependent kinase inhibitors such as CDKN2A have been reported in cutaneous squamous cell carcinomas associated with alterations in ALK in tumors such as lung cancer." (PMID 39273494, 2024). "Studies have demonstrated that the CDKN2A gene mutation in patients with lung cancer has diagnostic significance for lung cancer and is a separate risk factor impacting the patients' postoperative survival." (PMID 38206516, 2024). "Other studies have shown that lung cancer patients with EGFR mutation combined with CDKN2A deletion mutation have poor response to EGFR-TKI drugs." (PMID 36937524, 2023). "This is consistent with our previous findings of the least favorable outcome of lung cancer patients harboring CDKN2A/B loss treated with ICIs in another cohort with both KRAS-mutated and KRAS wildtype patients." (PMID 36230855, 2022). "The p16 protein, which is encoded by CDKN2A, was found to play an important role as a tumour suppressor in many cancers, such as pancreatic and lung cancer." (PMID 35637955, 2022). "Loss of CDKN2A has been associated with poor clinical prognosis and tumor progression in lung cancer." (PMID 35253368, 2022). "CDKN2A is a cell cycle regulator whose loss of function is closely related to the progression, prognosis, and treatment of lung cancer." (PMID 36712848, 2022). "A homozygous deletion mutation of CDKN2A (P16) was found in 31 patients with 127 EGFR mutations in lung cancer treated with EGFR-TKIs." (PMID 35004697, 2021). "In some lung cancer patients, CDKN2A deletion and EGFR mutation are coexistent to mediate poor drug response." (PMID 33959491, 2021). "EGFR mutation and CDKN2A deletion co-occurred in a subgroup of lung cancer and were associated with the clinical outcome of EGFR inhibitor treatment." (PMID 33959491, 2021). "CDKN2A inactivation is frequent in lung cancer and occurs via homozygous deletions, point mutations, or methylation of promoter regions." (PMID 35004299, 2021). "We found the frequent loss of CDKN2A was associated with its downregulation in lung cancer, and siRNA‐mediated CDNKN2A knockdown significantly stimulated cell proliferation, invasion, and migration." (PMID 33155773, 2020).
lung carcinoma (continued). "The suppressed expression of MTAP predominantly contributed to the oncogenic signaling in CDKN2A‐deficient lung cancer." (PMID 33155773, 2020). "Further analysis uncovered the relatively low expression of CDKN2A transcript in lung cancer patients with CDKN2A depletion, which highlighted the important contribution of genomic loss to the downregulation of CDKN2A." (PMID 33155773, 2020). "Here, we retrieved the publicly available database and unraveled the causal relationship between genomic deletion and downregulation of CDKN2A in lung cancer patients, which clinically associated with unfavorable prognosis." (PMID 33155773, 2020). "Mechanistically, we identified MTAP as a positively correlated gene with CDKN2A in lung cancer, which was significantly downregulated in CDKN2A‐deficient cells." (PMID 33155773, 2020). "In fact, methylation of the CDKN2A promoter CpG island has been observed in the sputum of subjects at risk for lung cancer 3 years prior to diagnosis and in the sputum of asymptomatic heavy smokers." (PMID 17967182, 2007). "A recent analysis of prospectively collected sputum showed CDKN2A methylation in 39% of cases and 25% of controls; methylation of this gene was associated with an elevated risk of lung cancer." (PMID 17967182, 2007). "Additionally, a significant loss of CDKN2A copy number, ranging from 27% to 28%, has been observed in patients with lung cancer with brain metastasis." (PMID 39323996, 2024). "Additionally, insights gleaned from MSK data within the TCGA database revealed that in patients with stage I lung cancer, the loss of CDKN2A copy numbers was associated with poor OS." (PMID 39323996, 2024). "In KRAS-mutated lung cancer, CDKN2A mutation was associated with worse survival on imunotherapy." (PMID 38310130, 2024). "The most studied TSG in lung cancer development is CDKN2A, which encodes p16INK4a and p14arf." (PMID 38335396, 2024). "The loss of Cdkn2a is often found in human lung cancers including LUAD and LUSC3." (PMID 38167599, 2024). "CDKN2A has multiple hotspots and has been associated with poor survival in lung cancer." (PMID 38473427, 2024). "Lung cancer is associated with genetic mutations in CDKN2A, such as genomic deletions." (PMID 37265472, 2023). "Therefore, EGFR mutation with CDKN2A (P16) deletion mutation is associated with the development of lung cancer." (PMID 35004697, 2021). "Other targets linked to hypoxia such as Cdkn2a (cyclin-dependent kinase inhibitor 2A) or Vdac1 (voltage-dependent anion-selective channel 1) were identified in an innovative approach aiming to explore novel biomarkers for lung cancer in exhaled breath." (PMID 34298636, 2021). "Lung cancer patients with CDKN2A loss have poor overall and disease-free survival." (PMID 35004299, 2021). "For lung cancer, an early focus was to search methylated CDKN2A as a plasma diagnostic biomarker." (PMID 32849827, 2020). "Importantly, lung cancer patients with CDKN2A loss manifested relatively poor overall survival and disease‐free survival." (PMID 33155773, 2020). "We first analyzed the gain and loss of genomic fragments in lung cancer at genome‐wide level in the TCGA database with the cBioportal algorithm, and uncovered a characteristic depletion of genomic region in chromosome 9 across the CDKN2A coding sequence." (PMID 33155773, 2020).
lung carcinoma (continued). "CDKN2A is known to be a negative regulator of the cell cycle, and its transcriptional variants (p16INK4a, p14ARF and p12) showed different inhibitory effects on the A549 human lung cancer cell line." (PMID 33142748, 2020). "The frequent loss of CDKN2A associated with its down‐regulation in lung cancer." (PMID 33155773, 2020). "We tested this in U2OS human osteosarcoma that are deleted for the cell cycle regulatory gene CDKN2A (Catalogue of somatic mutations in cancer), and human lung cancer A549 cells that carry the K-Ras G12S oncogenic mutation (Catalogue of somatic mutations in cancer)." (PMID 26163656, 2015). "Interestingly, CDKN2A hypermethylation at the promoter CpG island been associated with progression of stage 1 lung cancer, suggesting the importance of continued inactivation of this gene during progression." (PMID 21731750, 2011). "Frequent deletions and mutations of CDKN2A (a negative regulator of cell cycle, also known as p16) in lung cancer were first observed in 1994 and hypermethylation and silencing was subsequently observed to occur in substantial numbers of cancers carrying an intact gene." (PMID 21731750, 2011). "Some somatic gene alterations in lung cancer have been linked to tobacco smoke, but few data are available on the role of asbestos fibers: Andujar and colleagues investigate the mechanism of P16/CDKN2A alterations in lung cancer including asbestos-exposed patients." (PMID 34071989, 2021). "Seven tumor suppressor genes (CDKN2A, CDH13, MGMT, MIR137, DAPK1, RARB, and RASSF1A) consistently exhibited hypermethylation in both lung cancer and in association with smoking exposure." (PMID 42073597, 2026). "In lung cancer, CDKN2A hypermethylation is common and has been detected in sputum samples years before clinical diagnosis, highlighting its potential as an early detection biomarker." (PMID 40191732, 2025). "Lung cancer patients with wild-type CDKN2A are less likely to experience disease progression following therapy compared with those with CDKN2A loss." (PMID 40909976, 2025). "Studies have demonstrated that the methylation of genes like CDKN2A (p16), MGMT, and RASSF1A can be identified in sputum samples from high-risk individuals before clinical diagnosis of lung cancer." (PMID 40191732, 2025). "Our bioinformatics analyses of transcriptomic data from human lung cancer samples demonstrated that high SIRT7 expression in tumors correlates with increased expression of genes normally repressed by ARF, exclusively in tumors harboring an intact CDKN2A locus." (PMID 39036727, 2024). "In lung cancer patients, high expression of DLD, DLAT, PHDA1, PHDB, and CDKN2A were associated with poor OS, while high expression of MTF1 was associated with longer OS." (PMID 39068453, 2024). "Previous research has shown a strong correlation between the clinical characteristics and prognosis of lung cancer patients and the degree of CDKN2A expression in lung cancer tissues." (PMID 38206516, 2024). "A recent study by UT MD Anderson Cancer Center found that when KEAP1, SMARCA4, and CDKN2A co-mutate with KRAS-G12C, KRASG12Ci monotherapy is ineffective in treating patients with advanced lung cancer." (PMID 38817907, 2024).
lung carcinoma (continued). "CDKN2A, identified as one of the DEGs, was notably upregulated in lung cancer-related genes, highlighting its specific and pivotal role in this context." (PMID 39734333, 2024). "Both CDKN2A abnormalities and MET amplification are associated with the disease progression and poor prognosis of lung cancer patients." (PMID 36937524, 2023). "In lung cancer, genes with methylated specific CpG islands included CDKN2A, RASSF1A, RARbeta, MGMT, GSTP1, CDH13, APC, DAPK, TIMP3, etc." (PMID 36875059, 2023). "Two of them, cyclin-dependent kinase inhibitor 2A (CDKN2A), which encodes the tumor suppressor p16, and O-6-methylguanine-DNA methyltransferase (MGMT), are methylation targets shared by COPD and lung cancer." (PMID 36765688, 2023). "Another study showed that among the 8 subjects with CDKN2A gene methylation, 3 subjects were diagnosed with lung cancer about 1 year after sampling." (PMID 36875059, 2023). "The cyclin-dependent kinase inhibitor 2A (CDKN2A) gene inactivation is significantly more common in SqCLC than in other non–small cell lung cancer (NSCLC) subtypes." (PMID 36835617, 2023). "In another genomic study of BM of various origin, several potentially actionable genomic alterations were associated with lung cancer BM, including AKT1, AURKA, CDK6, EGFR, MEK1, MET, and PIK3CA gene amplifications and CDKN2A deletions." (PMID 36561283, 2022). "Mutations in other tumor suppressors (RB1, CDKN2A, SMARCA4/BRG1) are also frequently implicated in lung cancer." (PMID 35573694, 2022). "In lung cancer, patients with STK11 mutations showed resistance to anti-PD-1 inhibitors, and deletions in CDKN2A were negatively correlated with T-cell markers in different cancer types." (PMID 36138075, 2022). "It was found that the frequent deletion of CDKN2A was related to the downregulation of CDKN2A in lung cancer." (PMID 36338763, 2022). "In a phase II clinical trial (NCT01291017), advanced non–small cell lung cancer patients with wild-type RB and inactive CDKN2A can benefit from palbociclib treatment." (PMID 35912232, 2022). "Lung cancer patients were separated into high- and low-CDKN2A subtypes based on the median CDKN2A expression levels." (PMID 35004299, 2021). "For example, secondary mutations in tumor suppressors, such as STK11 and CDKN2A, contribute to the KRAS independency in lung cancer cell lines." (PMID 34680229, 2021). "Genetic and epigenetic modifications in the CDKN2a locus have been well characterized in diverse cancers; the uncoupling of ARF mRNA and protein expression has also been observed in lung cancer." (PMID 32759846, 2020). "Our previous analysis suggested the potential tumor suppressor role of CDKN2A in lung cancer, which prompted us to clarify this in cell culture." (PMID 33155773, 2020). "Profiling the epithelial‐mesenchymal transition‐related molecular markers demonstrated decreased CDH1, TJP1, and OCLN and increased ZEB1, FN1, and EZH2 in response to CDKN2A silencing in lung cancer cells." (PMID 33155773, 2020). "Our results also highlighted the predominant roles of MTAP in mediating the antitumoral activities of CDKN2A in lung cancer cells." (PMID 33155773, 2020). "Studies observed hypermethylation of CDKN2A in the plasma of patients with lung cancer as compared to cancer-free controls." (PMID 32849827, 2020). "ARF-null mice generated by specifically targeting exon 1β in the CDKN2a locus spontaneously develop numerous tumors, including sarcomas, lymphomas, and lung carcinomas, resulting in death within one year." (PMID 32759846, 2020).
lung carcinoma (continued). "We next sought to clarify the potential effects of CDKN2A on cell migrative and invasive behaviors in lung cancer cells." (PMID 33155773, 2020). "ARID1A and CDKN2A are also on the top 20 cancer gene list in breast, colon, and lung cancers, and are found in an average of 7.4% and 4.2% cases, respectively, across all four common cancer types." (PMID 32570879, 2020). "Our data were in support of the antitumor properties of CDKN2A, deletion of which was notably detected in many lung cancer patients, and therefore, suggested a fundamental role in the tumorigenesis of this disease." (PMID 33155773, 2020). "Mechanistically, we unraveled that MTAP, which was positively correlated with CDKN2A, predominantly mediated the antitumoral function of CDKN2A in lung cancer." (PMID 33155773, 2020). "CDKN2A is a well-known tumor suppressor gene in lung cancer, and it is frequently inactivated in LUSC." (PMID 32434476, 2020). "The downregulation of CDKN2A was long recognized as a major player in the tumorigenesis of lung cancer via epigenetic suppression." (PMID 33155773, 2020). "We further demonstrated that ectopic CDKN2A expression remarkably inhibited cell proliferation and viability in lung cancer cells, while siRNA‐mediated CDKN2A knockdown greatly promoted cell proliferation and viability." (PMID 33155773, 2020). "CDKN2A is frequently inactivated in many malignant tumors, and is closely related to lung cancer progression." (PMID 32445554, 2020). "We next investigated the potential linkage between CDKN2A depletion and clinical outcomes in lung cancer patients via analyzing the survival curve." (PMID 33155773, 2020). "Most importantly, here, we further identified a positive correlation between CDKN2A and Methylthioadenosine Phosphorylase (MTAP, OMIM association number, 156540) in lung cancer." (PMID 33155773, 2020). "Increased methylation levels have been detected in APC, MLH1, and CDKN2A genes in industrial workers with lung cancer." (PMID 30871143, 2019). "First, loss of CDKN2A/p16 is the most common somatic genetic or epigenetic event in NSCLC and is mutually exclusive with loss of RB function in lung cancer." (PMID 30647837, 2018). "The epistatic retinoblastoma (RB: CDK4/6: Cyclin D: CDKN2a/p16) signaling pathway is targeted for somatic or epigenetic alterations in essentially 100% of lung cancer samples." (PMID 30647837, 2018). "The most frequently epigenetically inactivated TSG in lung cancer are the Ras association domain family 1A (RASSF1A) and the cyclin-dependent kinase inhibitor 2A (CDKN2A/p16) genes." (PMID 28634396, 2017). "In lung cancer, cyclin-dependent kinase inhibitor 2A (CDKN2A) methylation has been identified as an early marker of disease in smokers." (PMID 28386299, 2017). "The inactivation of CDKN2A by promoter hypermethylation was observed in leukemia, colorectal, gastric, esophagus, and lung cancers." (PMID 26862903, 2016). "Abnormal CDKN2A promoter hypermethylation has been found in several types of tumor, and the frequency of CDKN2A promoter methylation ranged from 17% to 80% (median 44%) in lung cancer tissues." (PMID 27517925, 2016). "Specifically using MSP, they looked at methylation of CDKN2A, MGMT, DAPK and GSTP1, genes whose aberrant methylation profiles have already been shown to associate with lung cancer risk or diagnosis." (PMID 23870182, 2013).